LRG1 (leucine rich alpha-2-glycoprotein 1)
Diseases named in the same sentence as LRG1 in open-access papers (continued):
Sharing a sentence is not in itself a finding about the gene and the disease.
diabetes (continued). "Subsequently, it is assumed that plasma LRG1 is elevated in patients with hypertension, hyperlipidemia, and diabetes before developing into STEMI compared with healthy subjects." (PMID 38742172, 2024). "Elevated levels of LRG-1 are found in a multitude of pathological conditions including eye diseases, diabetes, infections, autoimmune diseases, and cancer." (PMID 38413424, 2024). "Systemic and local elevation of LRG1 levels has been observed in patients with systemic diseases, such as diabetes mellitus and RA, suggesting a correlation with the pathology of the disease and demonstrating its effectiveness as a new diagnostic marker." (PMID 38656694, 2024). "LRG1 has been reported to be involved in multiple human conditions including diabetes and inflammatory disorders." (PMID 36744850, 2023). "Since then, an increasing number of publications have reported the involvement of LRG1 in multiple human conditions including cancer, diabetes, cardiovascular disease, neurological disease, and inflammatory disorders." (PMID 35062948, 2022). "In the kidney, dysfunction is also a major co-morbidity of long-term diabetes, so it is particularly relevant that in a 3-year prospective study, higher circulating levels of LRG1 were predictive of diabetic nephropathy progression in T2DM patients." (PMID 35062948, 2022). "As LRG1 can affect both existing and newly formed vessels, it is tempting to speculate that counteracting LRG1 angiopathic activity might be beneficial in a wide range of diseases, ranging from cancer to the vascular complications associated with inflammation and diabetes." (PMID 35062948, 2022). "A substantial increase in LRG1 expression has been reported in cancer and diabetes, both responsible for a great burden of morbidity and mortality worldwide, but also in infections, cardiovascular, kidney, lung, neurological and autoimmune disorders." (PMID 35062948, 2022). "In another study, increased urinary LRG1 levels in type 1 diabetes mellitus (T1DM) patients were found compared to healthy siblings." (PMID 35062948, 2022). "Several biomarkers consisting of apolipoprotein A-IV, monocyte differentiation antigen CD14, and LRG1 demonstrated their influences on the differentiation between diabetes and early pancreatic cancer." (PMID 35095520, 2021). "We previously showed that LRG1 potentiates diabetes-induced angiogenesis in GECs during early diabetic kidney disease." (PMID 34244474, 2021). "LRG1 is usually used as a biomarker of tumors, appendicitis, diabetes complications, and inflammatory disease." (PMID 34675320, 2021). "Our study revealed a particularly high rate of PAOD in patients with higher plasma LRG1 levels, even after adjustment for diabetes, albumin and hsCRP levels." (PMID 32249825, 2020). "Finally, additional studies are warranted to confirm the vascular origin of increased LRG1 expression in human diabetic retina and validate our findings obtained in HRECs and in mice." (PMID 41124286, 2025). "Indeed, accumulating evidence indicates that LRG1 is upregulated in the plasma and urine of people with diabetes, hence it can serve as a biomarker for PDR." (PMID 38745756, 2024). "Plasma LRG1 at admission was not linked with a history of hypertension (P = 0.412) or diabetes mellitus (P = 0.585), while plasma LRG1 at admission was negatively related to a history of hyperlipidemia (P = 0.017) in patients with STEMI." (PMID 38742172, 2024). "However, in wounds from diabetic mice, as well as from patients with diabetes, LRG1 expression was markedly enhanced and in mice was shown to result in delayed wound closure." (PMID 38745756, 2024). "Thus, LRG1 has now been reported to damage vessels in various disorders including cancer, diabetes, chronic kidney disease, ocular disease, and lung disease and the signaling processes that drive this dysfunction are being defined." (PMID 38745756, 2024). "Aberrant LRG1 glycosylation is recognised in multiple diseases, including diabetes." (PMID 37121976, 2023).
diabetes (continued). "LRG1, or leucine-rich α–2 glycoprotein 1, has been shown to promote angiogenesis by modulating TGF-β signaling, and this process has been implicated in various complications of diabetes." (PMID 36346018, 2022). "Another protein, leucine-rich alpha-2-glycoprotein 1 (LRG-1), although essential for timely wound closure, is elevated in diabetic patients and mice, where it causes NETosis which, when excessive such as in diabetics, actually impairs normal wound healing." (PMID 36082273, 2022). "In addition to its physiological functions, LRG1 has been reported to participate in several pathological conditions, including cancer and diabetes." (PMID 35955698, 2022). "The function of LRG1 under normal circumstances remains unclear, but in a variety of pathologies including cancer and diabetes LRG1 levels are significantly increased." (PMID 34445590, 2021). "The current investigation is the first to show the systemic elevation of LRG1 levels in diabetes." (PMID 29240802, 2017). "Since LRG1 is almost undetectable in a healthy human eye, its elevated expression in the vitreous in diabetes is most likely to be due to activated local production in response to disease, but it may also derive from the plasma as a consequence of vascular leakage." (PMID 38745756, 2024). "Therefore, we speculate that the altered expression, secretion, and/or activity of an unknown factor in hyperglycemia and diabetes mellitus may induce LRG1 deglycosylation, allowing the activation of LRG1/LPHN2-mediated signaling." (PMID 37121976, 2023). "Our data from cancer studies indicate that LRG1 affects pericyte investment of vessels and would suggest, therefore, that in diabetes LRG1 may contribute to both early (development of vascular instability) and late (neovascularisation) events in its pathogenesis." (PMID 34987199, 2022). "It remains to be determined, however, whether diabetes per se (i. e., without retinopathy), like other inflammatory disorders, causes the upregulation of LRG1 in the systemic circulation." (PMID 29240802, 2017). "To address this gap, we analyzed LRG1 expression in post-mortem retinal tissues from donors with or without diabetes (type 1 or 2), including cases diagnosed with DR." (PMID 41124286, 2025). "Increased LRG1 levels were also detected in the plasma of type 2 diabetes mellitus (T2DM) patients with PDR compared to patients without diabetes, patients with T2DM without retinopathy and patients with non-proliferative diabetic retinopathy." (PMID 35062948, 2022). "The results suggested that diabetes-induced upregulation of s(P)RR, prorenin and LRG-1 did not stem from circulating leukocytes." (PMID 29240802, 2017). "Moreover, comparing subgroups of LD patients with vs. without insulin resistance/diabetes mellitus, with vs. without hepatic steatosis, and with generalised LD vs. partial LD does not show any significant differences in LRG1 serum levels." (PMID 39595649, 2024). "Moreover, higher LRG1 levels were observed in young diabetes mellitus type 1 patients when compared to non-diabetic controls." (PMID 35955698, 2022).
pancreatic cancer (24 papers, 2010 to 2025). "LRG1 is a novel angiogenic factor that was previously associated with a variety of cancers, including endometrial carcinoma, gastric, colorectal, and pancreatic cancers." (PMID 34208965, 2021). "Increased LRG1 expression in the serum has been demonstrated in ovarian cancer, non-small cell lung cancer, gastric cancer, pancreatic cancer, and leukemia." (PMID 38658967, 2024). "Previous studies have demonstrated that LRG1 is involved in the progression of tumors by promoting angiogenesis, including pancreatic cancer, lung cancer, bladder cancer, and colon cancer." (PMID 36681849, 2023). "Several potential mediators were identified in pancreatic cancer, such as LRG1 and LCN2, which can cross the attenuated BBB in the MBH." (PMID 35031523, 2022). "Recently, LRG1 has been implicated in regulating P38/MAPK pathway as it has been shown to promote cancer metastasis and proliferation in thyroid and pancreatic cancers through P39/MAPK signaling pathway." (PMID 35955698, 2022). "Glypican-1(GPC-1) is a potential biomarker for pancreatic cancer diagnosis, and human leucine rich alpha-2-glycoprotein 1 (LRG1) in urinary sEVs is a potential biomarker for diagnosis of NSCLC." (PMID 34685415, 2021). "In a study of pancreatic cancer, knock down of LRG1 mRNA decreased viability of two cell lines and overexpression of LRG1 by gene transfection increased viability, proliferation, and cell migration." (PMID 34692699, 2021). "MAPK pathway is known as one of the key signaling pathways that regulate the pathological process of pancreatic cancer, and LRG-1 was reported to modulate the activation of MAPK signaling downstream protein." (PMID 30760292, 2019). "Human LRG1 is a serum glycoprotein with five potential glycosylation sites, and has been found to be elevated in pancreatic cancer and lung cancer." (PMID 25799488, 2015). "Our data was in line with the other studies indicating that increased LRG1 expression was presented in ovarian cancer, non-small cell lung cancer, gastric cancer, pancreatic cancer and leukemia." (PMID 26517349, 2015). "Elevated plasma LRG1 has also been reported in patients with pancreatic cancers, though its relationship to the presence or absence of biliary obstruction in these patients was not reported." (PMID 21970875, 2011). "LRG1 levels have also been shown to be elevated in the medium and low abundance serum proteins of lung and pancreatic cancers." (PMID 20546617, 2010). "Differential expression techniques employing affinity depletion of high abundance proteins and 2 D electrophoresis have found serum LRG1 to be upregulated in lung and pancreatic cancer." (PMID 20831812, 2010). "In previous literatures, LRG1 showed promise to indicate inflammation in a mouse model, granulocytic differentiation, and was listed as one of the altered proteins in cancer proteomic studies, such as hepatocellular carcinoma, pancreatic cancer, and lung cancer." (PMID 23284758, 2012). "Elevation of LRG1, SPARCL1, S100A8, Plastin-2 may be of special significance in a small but significant percentage of patients which have increased risk for prolonged development of a disease spectrum that connects AP, RAP, and chronic pancreatitis with emergence of pancreatic cancer." (PMID 30214418, 2018). "Previous studies using serum samples of PDAC patients who were newly diagnosed showed that the combination of LRG1, TIMP1 and CA19-9 biomarkers increased the accuracy of pancreatic cancer detection by 13.2% with a specificity greater than 99%, as compared to that using CA19-9 alone." (PMID 37173913, 2023). "Increased LRG1 expression has been demonstrated in ovarian cancer, non-small cell lung cancer, gastric cancer, pancreatic cancer and leukemia." (PMID 26517349, 2015).
pancreatic cancer (continued). "In patients with colorectal and pancreatic cancer, LRG1 levels tends to be positively correlated with more advanced cancer stages and worse prognosis, and the PPARβ/δ agonist, GW501516, significantly increases LRG1 expression, strongly indicating that LRG1 is a direct target of PPARβ/δ." (PMID 37251321, 2023). "Indeed, epidermal growth factor receptor (EGFR) has been shown to mediate LRG1 activity in pancreatic cancer cells, metastatic melanoma cells, and corneal epithelium during wound repair, whereas the IL-6/STAT3 axis appears to modulate LRG1-driven neutrophil chemotaxis." (PMID 35062948, 2022). "It is likely that these myeloid cells and blood borne biomarkers of pancreatic cancer act in symphony to induce some of the observed local changes in the MBH, which is confirmed by the high level of co-regulation between a number of these transcripts (e.g. lrg1, Plin4, Lcn2 and Icam1)." (PMID 35031523, 2022).
rheumatoid arthritis (23 papers, 2017 to 2026). A chronic, systemic autoimmune disorder characterized by inflammation in the synovial membranes and articular surfaces. "Lrg1 expression was shown to be associated with disease activity in different human diseases such as rheumatoid arthritis, ulcerative colitis and Crohn’s disease." (PMID 32183784, 2020). "LRG1 is a pleiotropic secreted pro-inflammatory glycoprotein whose overexpression has been linked to a number of autoimmune diseases such as rheumatoid arthritis and Crohn disease, as well as neurodegenerative diseases such as Parkinson disease." (PMID 32692761, 2020). "LRG1 has been identified as an inflammatory protein in human serum and highly expressed in various kinds of autoimmune diseases, including rheumatoid arthritis and lupus nephritis." (PMID 35935760, 2022). "Levels of LRG1 are increased in many inflammatory conditions including sepsis, appendicitis, rheumatoid arthritis and cancer." (PMID 30774579, 2019). "LRG1 is known to be a biomarker for various inflammatory diseases, including rheumatoid arthritis, ulcerative colitis, and asthma, and also functions as an endothelial cell mitogen for tumor and retinal neovascularization." (PMID 29240802, 2017). "Studies have shown elevated LRG1 levels in patients suffering from rheumatoid arthritis." (PMID 38667022, 2024). "In particular, serum LRG1 has been identified as a useful biomarker for monitoring disease activity in patients with adult-onset Still's disease, psoriasis lupus nephritis, rheumatoid arthritis and vasculitis." (PMID 35062948, 2022). "The role of LRG1 as a pro-inflammatory mediator is more clearly established in the pathogenesis of rheumatoid arthritis (RA), where high levels of Th17 cells and Th17-related cytokines, including TNFα and IL-6, cause severe joint destruction and correlate with poor prognosis." (PMID 35062948, 2022). "This study aimed to investigate the correlation of serum LRG1 level with disease features and response to biologics in rheumatoid arthritis (RA) patients." (PMID 40665055, 2025). "In addition, LRG1 has been identified as a useful biomarker to distinguish between patients with active or inactive systemic juvenile idiopathic arthritis and in patients with rheumatoid arthritis during Tocilizumab treatment 8,59." (PMID 35318338, 2022). "Moreover, LRG1 is identified as an inflammatory protein in human serum and highly expressed in various kinds of benign inflammatory and autoimmune diseases, including suspected acute appendicitis of children, activated ulcerative colitis, rheumatoid arthritis, adult-onset Still’s disease and asthma." (PMID 32252660, 2020). "In previous study, serum LRG1 concentrations correlated with disease activity in SLE, rheumatoid arthritis, Crohn’s disease, ulcerative colitis and adult-onset Still’s disease." (PMID 32252660, 2020). "The level of LRG1 was also found to be correlated with CRP, erythrocyte sedimentation rate (ESR), and disease activity score 28 (DAS28), but not with the serum TNF-α levels in rheumatoid arthritis (RA)." (PMID 36569927, 2022).
acute appendicitis (21 papers, 2016 to 2025). "In contrast to previous studies, in this cohort serum LRG1 was associated with decreased odds of appendicitis, shedding some doubt over the clinical utilization of serum LRG1 as a biomarker for appendicitis in children." (PMID 40208339, 2025). "In the appendicitis context, LRG1 has been analyzed in serum, urine, and saliva, with varying – but sometimes very promising—diagnostic accuracy, especially for urine LRG1." (PMID 40208339, 2025). "In the logistic regression analysis of all children with suspected appendicitis, increased serum LRG1 was associated with a decreased odds of appendicitis (OR 0.96 [95% CI 0.93–0.99], p = 0.008)." (PMID 40208339, 2025). "The aim of this study is to evaluate the diagnostic accuracy of leucine-rich α-2-glycoprotein 1 (LRG1) in saliva as a novel biomarker for acute appendicitis in the pediatric population." (PMID 37047015, 2023). "Our study corroborated the findings on the diagnostic potential of salivary LRG1 in children with acute appendicitis." (PMID 37047015, 2023). "Accordingly, the objective of our study was to evaluate the association between the salivary biomarker LRG1 and acute appendicitis in the pediatric population." (PMID 37047015, 2023). "Multiple biomarker studies in humans have shown that increased LRG1 is associated with not only obesity but also conditions involving cell death and inflammation, such as appendicitis, solid tumors and autoimmune diseases." (PMID 36346018, 2022). "Another inflammation-associated target is LRG1, mainly contributing to inflammatory diseases such as acute appendicitis, inflammatory bowel disease, diabetic kidney disease, and to various cancer types." (PMID 35681422, 2022). "The authors of this study assessed LRG1 as a potential diagnostic tool because its marked expression is believed to represent an increased inflammatory process in patients with appendicitis." (PMID 34064691, 2021). "Notably, higher serum LRG1 concentrations were inversely associated with appendicitis (OR 0.96 [95% CI 0.93–0.99], p = 0.008." (PMID 40208339, 2025). "It was important to determine whether there was any basis for expanding this type of study regarding LRG1 diagnostic abilities in acute appendicitis." (PMID 34064691, 2021). "Overall, LRG1 is a valuable addition to the growing landscape of serum biomarkers for acute appendicitis." (PMID 41153524, 2025). "Recent studies have identified salivary biomarkers such as leucine-rich α-2-glycoprotein 1 (LRG1) and irisin as potential non-invasive tools for diagnosing acute appendicitis in children." (PMID 40871545, 2025). "Leucine rich alpha-2 glycoprotein 1 (LRG1) has emerged as a promising biomarker for appendicitis, especially in pediatric patients." (PMID 40208339, 2025). "A recent study reported significantly higher salivary LRG1 levels in children with confirmed appendicitis, with a specificity of 100% at a certain cut-off, though sensitivity was limited." (PMID 40871545, 2025). "The median LRG1 concentration was significantly higher in children with appendicitis (233.5 ng/mL; IQR 174.8–368.4) compared to controls (55.9 ng/mL; IQR 36.5–95.6), with p < 0.0001." (PMID 41153524, 2025). "Leucine-rich alpha-2-glycoprotein 1 (LRG1) has recently emerged as a promising serum biomarker for diagnosing acute appendicitis." (PMID 41153524, 2025). "The median salivary LRG1 level was significantly higher in children with appendicitis (0.294 ng/μg of total salivary protein) compared to controls (0.126 ng/μg; p = 0.008)." (PMID 41153524, 2025). "The median salivary LRG1 level was significantly higher in the group of children with pathohistologically confirmed acute appendicitis compared to the control group: 233.45 ng/mL (IQR 114.9, 531.2) vs. 55.95 ng/mL (IQR 51.5, 117.9), p < 0.001." (PMID 37047015, 2023). "Our study demonstrated a statistically significant elevation of salivary LRG1 in children with acute appendicitis compared to the control group." (PMID 37047015, 2023).